ATXN7L1 (ataxin 7 like 1)
Synonyms: ATXN7L4; KIAA1218; MGC33190
Tractability: No criterion of Open Targets' tractability assessment is met for any kind of drug.
Gene: Protein-coding gene on chromosome 7 (105,604,772 to 105,876,599, reverse strand). Ensembl gene ENSG00000146776.
Subcellular location (Human Protein Atlas): Cytosol; Nucleoplasm
Gene Ontology:
Molecular function: protein binding
Genetic constraint (gnomAD): Loss-of-function variants: 14 observed, 63.46 expected, observed/expected ratio (o/e) 0.22, 90% interval 0.14 to 0.34. The upper end of that interval is the gene's LOEUF score, 0.34, which puts it in group 1 of 6, group 1 being the genes least tolerant of losing a copy. Missense variants: 967 observed, 1,107.5 expected, observed/expected ratio (o/e) 0.87, 90% interval 0.83 to 0.92. Synonymous variants: 436 observed, 450.08 expected, observed/expected ratio (o/e) 0.97, 90% interval 0.89 to 1.05.
Homologues: Orthologues: chimpanzee ATXN7L1 (99% identical), macaque ATXN7L1 (98% identical), dog ATXN7L1 (94% identical), guinea pig ATXN7L1 (92% identical), pig ATXN7L1 (92% identical), mouse Atxn7l1 (89% identical), rabbit ATXN7L1 (83% identical), rat Atxn7l1 (75% identical), tropical clawed frog atxn7l1 (70% identical), zebrafish atxn7l1 (20% identical). Paralogues in human: ATXN7 (38% identical), ATXN7L2 (27% identical), ATXN7L3 (9% identical), ATXN7L3B (1% identical).
Diseases named in the same sentence as ATXN7L1 in open-access papers:
ATXN7L1 is named in the same sentence as 3 diseases in open-access papers, as found by Europe PMC text mining. Sharing a sentence is not in itself a finding about the gene and the disease. The quoted sentences say what the papers report.
breast carcinoma (1 paper, 2024). "cg17242362 (ATXN7L1) and cg17403702 (ARFIP2) were hypomethylated in breast cancer alone." (PMID 38336771, 2024).
ATXN7L1 also shares sentences with these, for which no sentence is quoted: lung carcinoma (1 paper); Obesity (1).